EGFR (epidermal growth factor receptor)
Diseases named in the same sentence as EGFR in open-access papers (continued):
Sharing a sentence is not in itself a finding about the gene and the disease.
cancer (continued). "Aberrant activation and deregulated expression of EGFR has been found to be important for cancer cell proliferation, survival and invasion as well as resistance to chemotherapy." (PMID 31139331, 2019). "They found that combination treatment with EGFR inhibitor (erlotinib) and DNA-damaging chemotherapy (doxorubicin) led to substantial killing of cancer cells, but only when the EGFR inhibition was used before the chemotherapy by at least 4 h." (PMID 30890944, 2019). "The antiproliferative activity of curcumin in cancer cells is based, among others, on the disruption of the EGFR/EGF/TGFα autocrine loop." (PMID 30871021, 2019). "In the single-cell model, eleven drugs were identified as p-EGFR-targeting drugs, but in the cancer spheroid model, only two drugs were identified as highly efficient p-EGFR-targeting drugs." (PMID 31614722, 2019). "An additional factor related to the cancer microenvironment that can induce resistance to EGFR-TKIs is hypoxia, which is present to a variable extent in metabolically active solid tumors such as NSCLC." (PMID 31266248, 2019). "EGFR signaling is frequently deregulated in cancer and contributes to various features of malignancy." (PMID 30910997, 2019). "In this study, PDOs were generated from cancer patients enrolled in Phase 1/2 clinical trials and drug responses (anti-EGFR monoclonal antibodies, regorafenib, and TAS-102) were evaluated both ex vivo and in PDO-derived xenografts." (PMID 31195689, 2019). "EGFR‐mediated Akt activation is associated with PD‐L1 expression, which can be reduced by EGFR inhibitors in cancer cell lines carrying activated EGFR." (PMID 31493351, 2019). "Epidermal growth factor receptor (EGFR) signaling is a key pathway for cell proliferation, migration and invasion in cancer in general." (PMID 31052302, 2019). "Together, we herein established the RTK-initiated transcription regulatory network, which highlighted transcriptional factors ATF4 and MYC as the key nodes in preferentially reprogramming the metabolic network in cancers with aberrant EGFR or FGFR." (PMID 31221965, 2019). "Altogether, our study has provided a novel, combinatory therapeutic strategy for effectively treating patients with EGFR-driven cancer." (PMID 31462678, 2019). "Given that E2-treated astrocytes activate both EGFR and TrkB ligands on brain metastatic cancer cells and the majority of human BM are EGFR+, we assessed how EGFR and TrkB activation contributed to signaling and metastatic traits in EGFR+TrkB+ TNBC cells." (PMID 30796353, 2019). "As a result, overexpression of TNS4 stabilized EGFR and enhanced its oncogenic signaling in cancer cells." (PMID 31052206, 2019). "The scientists transfected donor cells with let-7a, purified the exosomes from the culture supernatant and modified their surface with the peptide to deliver the miRNA to EGFR-expressing cancer tissues." (PMID 30901915, 2019). "EGFR, expressed broadly on normal human epithelial tissue, plays a prominent role in the progression of several cancers, including CRC." (PMID 30841571, 2019). "Serving as an activator of the MAPK, PI3K, and KRAS pathways, EGFR contributes to proliferation and metastasis of cancer cells and can be activated upon UV exposure." (PMID 30683916, 2019). "We describe furfuryl derivatives of 4-allyl-5-[2-(4-alkoxyphenyl)-quinolin-4-yl]-4H-1,2,4-triazole-3-thiol that bind to and weakly inhibit EGFR tyrosine phosphorylation and induce strong endocytic degradation of the receptor in cancer cells." (PMID 31374910, 2019). "The existence of KID pro-survival function of EGFR has also been revealed in different types of cancer cells involving several cellular functional domains that include the plasma membrane, the autophagic machinery, and the mitochondrion." (PMID 31508364, 2019).
cancer (continued). "The EGFR and its ligands are overexpressed in many human cancers, and dysregulation of the EGF/R network at multiple levels signals a poor prognosis." (PMID 31805097, 2019). "Cetuximab (Cet) is a commonly adopted monoclonal antibody that targets epidermal growth factor receptor (EGFR) to inhibits the EGF signaling in cancer cells." (PMID 30798640, 2019). "There were two main transfection methods (lentivirus and retrovirus) with various cancer-specific antigens (EGFR, CEA, HER2, etc.)used in these studies." (PMID 30886654, 2019). "They restrict the influence of EGFR downstream signaling solely to the perimembrane area, which is mostly involved in cell migration, therefore strengthening the effect of EGFR signaling on cancer cell motility." (PMID 31649529, 2019). "In other words, EGFR is indispensable for the survival of cancer cells that are innately resistant to EGFR kinase inhibitors." (PMID 31508364, 2019). "Potentially, there is a high expression of EGFR in MDA-MB-231 cells, which causes MDA-MB-231 to be invasive to cancer cells." (PMID 31772936, 2019). "We found that PFL decreased various integrins as well as EGFR in cancer cells by promoting internalization and autophagic degradation of these molecules, subsequently inducing caspase-8 dependent cell apoptosis." (PMID 31052260, 2019). "For instance, circFoxo3 has been reported to promote cell apoptosis and inhibit angiogenesis and cell cycle progression in cancer, while ciRS-7 promotes cell cycle progression by enhancing the EGFR/RAF1/MAPK pathway." (PMID 30744636, 2019). "EGFR utilizes a network of downstream signaling events leading to cell growth, proliferation, survival, angiogenesis, migration, and metastasis of many cancers." (PMID 31921216, 2019). "It is possible that our chalcones are likely to be effective only against cancers involving EGFR activation, since there are 2x106 EGFR receptors on the cancer cell surface with 1000-fold higher than normal cells." (PMID 30897725, 2019). "The EGFR/MAPK signaling pathway interacts with YAP positively to promote cancer progression, drug resistance, and metastasis in human NSCLC." (PMID 31387256, 2019). "Other research groups also found that in cancer cells the EGFR inhibitors erlotinib and dacomitinib can activate the interleukin-6 (IL6) / JAK / STAT3 signaling pathway, thereby leading to drug resistance." (PMID 30674340, 2019). "In cancer cells carrying EGFR mutants such as T790M, AREG expression is markedly elevated, but mostly limited to lung malignancies." (PMID 31493351, 2019). "Upon resistance to EGFR inhibition by monoclonal antibodies, cancer cells display a rewiring of feedback production, with an upregulation of genes that are able to sustain the signal and a downregulation of genes intrinsically able to dampen the EGFR pathway." (PMID 31052457, 2019). "Epidermal growth factor receptor (EGFR) is a widely distributed cell surface receptor involved in the physiological processes of cell growth and differentiation as well as in cancer metastasis." (PMID 30737360, 2019). "EGFR signaling has an important place and role in Pyk2 downstream signaling pathways, which will affect the growth and metastasis of cancer cells." (PMID 31368612, 2019). "It should be emphasized the importance of timely treatment with systemic antibiotics, topical application moisturizer, and avoiding discontinuation of EGFR inhibitors to achieve better clinical outcomes of cancer treatment." (PMID 31764850, 2019). "Dysregulated epidermal growth factor receptor (EGFR) expression and intracellular signaling play a crucial role in the etiology of many human cancers." (PMID 31557914, 2019).
cancer (continued). "EGFR is often overexpressed in many types of cancers, and is involved in signaling pathways to regulate cell proliferation, differentiation, and inhibition of apoptosis." (PMID 31754382, 2019). "Blockade of EGFR function inhibits the subsequent activation of EGFR downstream signaling cascades, which makes EGFR to be an optimal target for cancer therapy including cSCC." (PMID 30683916, 2019). "Erlotinib is a selective inhibitor that targets EGFR specifically, and has been in clinical trials for treatment of advanced solid malignancies." (PMID 31681603, 2019). "On the contrary, lnc-epidermal growth factor receptor (EGFR) leads to immunosuppressive state to cancer." (PMID 31850199, 2019). "The basic mechanism of EGFR activation and the role of EGFR signaling in cancer progression, has been well studied." (PMID 30777099, 2019). "The biological function of epidermal growth factor receptor (EGFR) in tumorigenesis and progression has been established in various types of cancers, since it is overexpressed, mutated, or dysregulated." (PMID 31013819, 2019). "The m6A mRNA methyltransferase METTL3 is upregulated in multiple types of cancers and can promote the m6A modification and expression of oncogenes including EGFR, TAZ, MYC, and SOX2." (PMID 30796352, 2019). "Aberrant expression of miRNAs has been implicated in various tumor types, including glioblastoma, and demonstrated to impact cancer cell proliferation, EGFR downstream signaling, as well as efficacy of several anti-EGFR-targeting therapeutic approaches." (PMID 32089685, 2019). "The abnormally high EGFR expression in cancer cells is explained as an initial reaction for cells to sense the change in mechanical cues to restore normal phenotype, but cancer cells resist this rescue program." (PMID 31438519, 2019). "The inhibition of CYP51A1 suppressed the accumulation of these C4-SBIs and reversed the EGFR inhibitor sensibilization, rescuing cancer cell viability and EGFR degradation." (PMID 30691248, 2019). "The mitotic abnormality as a consequence of genistein treatment in cancer cells cannot be fully understood based only on its EGFR inhibitory effects." (PMID 31100782, 2019). "Receptors that overexpressed in cancer cells, such as epidermal growth factor receptor (EGFR), have been investigated as binding sites for the targeted delivery of anti-cancer drugs." (PMID 31754382, 2019). "Similar links between response and FcγR-dependent mechanisms have been observed for additional cancer cell direct-targeting antibodies e.g., herceptin (anti-Her2) and cetuximab (anti-EGFR) in breast cancer and colorectal patients, respectively." (PMID 30930905, 2019). "Our present findings strongly support penfluridol as a repurposed drug for treating NSCLC, especially for the cancer types that are resistant to chemotherapy or EGFR TKIs." (PMID 31308361, 2019). "Targeting epidermal growth factor receptor (EGFR) with tyrosine kinase inhibitors (TKI) has been widely exploited to disrupt aberrant phosphorylation flux in cancer." (PMID 31374910, 2019). "This study showed that the COX-2 product, prostaglandin E2 (PGE2), is able to transactivate the EGFR pathway through four G protein-coupled receptors (GPCRs), resulting in the promotion of cancer cell growth and motility." (PMID 31817718, 2019). "It has been reported that combinatorial treatment of human cancers with anti-ErbB2 and anti-EGFR antibodies leads to more effective growth inhibition than either treatment alone." (PMID 31470510, 2019). "We chose SK-BR-3 and LNCaP cancer cells as models since they express both EGFR and PD-L1 on their surface." (PMID 31470510, 2019). "We and others reported that drugs that suppress survivin chemosensitize cancer cells to EGFR-TKIs and gemcitabine." (PMID 31614999, 2019). "Epigenetic modification is also a contributing factor in the development of resistance against EGFR inhibitors in cancer patients." (PMID 31013819, 2019).
cancer (continued). "We questioned how glutamine starvation affects signaling pathways initiated by EGFR and why the deficiency in glutamine strengthens the potency of VM26 to kill cancer cells." (PMID 31374910, 2019). "Light‐mediated binding of photoactive antibodies to their target, EGFR, was demonstrated using a robust and simple assay performed on the surface of cancer cells." (PMID 31609054, 2019). "Small molecule EGFR–tyrosine kinase inhibitors (EGFR-TKIs) and monoclonal antibodies against EGFR have shown strong efficacy in EGFR-dependent cancers." (PMID 31703435, 2019). "EGFR is implicated in various human cancers, while PTP1B can function either as an oncogene or tumor suppressor in various cancer types." (PMID 32039198, 2019). "It has been also shown that curcumin enhances the effect of some targeted drugs used in cancer such as gefitinib, an EGFR inhibitor, inducing autophagy-mediated apoptosis." (PMID 31744117, 2019). "We have developed an alternative means of targeting EGFR that relies on protein degradation through two consecutive routes, ultimately leading to cancer cell detachment-related death." (PMID 31374910, 2019). "Cancer patients treated with EGFR antagonists suffer not only from a wide range of side effects caused by loss of EGFR function in epithelial cells but also become more susceptible to infections probably due to effects on the immune system." (PMID 31921216, 2019). "In this study, we suggested that the effects of IVM were mainly mediated through inhibiting the EGFR pathway to reduce the transcription and expression of P-gp in the cancer cells." (PMID 31215501, 2019). "Previous studies also indicate that CD24 regulated EGFR signaling by inhibiting EGFR internalization and degradation in cancer cells." (PMID 31624236, 2019). "Whereas, cancer cells lacking the ARIH2 protein were able to produce more proteins that are needed for cancer cell growth, which resulted in them having increased resistance to EGFR inhibitors." (PMID 31741433, 2019). "Specifically, the anti-cancer effects of second-generation EGFR-TKIs on heregulin-expressing cancer cells by be sustained by pan-HER family inhibition." (PMID 31862929, 2019). "Naturally, resistance mechanisms vary among different cancers and the type of EGFR-directed agents used." (PMID 30700700, 2019). "Cyclosaplin also demonstrated effective binding affinities towards other cancer-related proteins, such as EGFR (−6.8 kcal/mol), VEGFR2 (−7.8 kcal/mol), PKB (−8.1 kcal/mol), p38 (−8.3 kcal/mol), PTEN-tumor suppressor (−6.3 kcal/mol), and MMP-9 (−7.3 kcal/mol)." (PMID 31731771, 2019). "Many studies have investigated the role of EGFR in cancer metabolism, particularly glucose metabolism in cancer cells." (PMID 30735525, 2019). "When combined with Vγ9Vδ2 T cells this construct enhanced the cytolytic response of the Vγ9Vδ2 T cells against EGFR+ cancer cell lines in vitro as well as in xenografted mice." (PMID 31695800, 2019). "EGFR signaling is known as a molecular integration site in pathological states such as cardiovascular dysfunction and cancer and the inhibition of this receptor has become a common treatment in the management of the latter." (PMID 31534849, 2019). "On the other hand, studies have shown that in addition to cancer genesis and development, EGFR also plays important roles in stimulating angiogenesis through very complicated biological processes." (PMID 31783917, 2019). "MAPKs in numerous cancers are well characterized as the main downstream signaling factors of EGFR to drive carcinogenesis and cancer progression." (PMID 30975171, 2019). "The definition of the mutational landscape of NSCLC has allowed the identification of actionable cancer genes such as EGFR, ALK, ROS1, BRAF and the development of targeted therapies." (PMID 31200752, 2019). "The results from the Pathview analysis showed that 11 genes were activated in EGFR tyrosine kinase inhibitor resistance pathways, and six of these genes were cancer-related genes." (PMID 31993418, 2019).
cancer (continued). "Treatment of malignant cancer cells with 213Bi-anti-EGFR-MAb induced intense DNA double-strand breaks, resulting in cell death as monitored via clonogenic survival." (PMID 31165773, 2019). "Several monoclonal antibodies (mAbs), such as the chimeric anti-EGFR mAb cetuximab, have been successfully introduced into clinical practice to treat cancer patients." (PMID 31852956, 2019). "By acting on multiple targets including PLK1, EGFR, and ER, genistein is a promising compound for cancer prevention and treatment." (PMID 31100782, 2019). "These scores were also cancer-associated epidermal growth factor receptor (EGFR) signaling and cancer pathways." (PMID 31772663, 2019). "Overall, these proposed functions can explain why the nuclear accumulation of EGFR seems to be selected in cancer cells, especially in relapsing tumors." (PMID 31426451, 2019). "We first classified these variants for which sufficient evidence exists that the corresponding amino acid change is a driver in cancer (e.g., EGFR p.(Leu858Arg) or JAK2 p.(Val617Phe))." (PMID 31888289, 2019). "Dr. John Mendelsohn is credited for the concept of targeting the epidermal growth factor receptor (EGFR), providing the first evidence of anticancer activity of antagonist anti-EGFR mAb, and developing the Erbitux (Cetuximab) drug for cancer patients." (PMID 31798764, 2019). "PD-L1 expression has been found to be upregulated by EGFR overexpression in several types of cancer cells, suggesting us to investigate on a dual EGFR and PD-L1 targeting strategy." (PMID 31470510, 2019). "After initial promising results of EGFR-targeted therapies such as cetuximab, therapeutic resistance poses a challenging problem and limits the success of effective anti-EGFR cancer therapies in the clinic." (PMID 30650638, 2019). "The epidermal growth factor receptor (EGFR) tyrosine kinase family was the first growth factor receptor family to be identified in cancer cells." (PMID 31438559, 2019). "Cancer cells use oncogene protein signaling, such as EGFR and HER-2, for survival and proliferation." (PMID 31717302, 2019). "Conclusion:111In-EGF-LP-Dox designed for concurrent chemo-radionuclide therapy showed specificity for and cytotoxicity towards EGFR-overexpressing cancer cells." (PMID 31534505, 2019). "Chalcones, or 1,3-diphenyl-2-propene-1-ones, are in the class of agents that have shown a promising therapeutic efficacy against several types of cancer and also display characteristics of an EGFR inhibitor." (PMID 30897725, 2019). "It has been demonstrated that curcumin downregulates EGFR in multiple cancer cells including NSCLC and subsequently inhibits its cell proliferation." (PMID 31817718, 2019). "Due to the pro-metastatic effects of EGFR signals in cancer cells, other than the cytotoxicity induced by Gefitinib, the function of SCD1 in the ability to migrate and invade A549 and H1573 cell lines was estimated." (PMID 31019378, 2019). "Dysregulated signaling via the epidermal growth factor receptor (EGFR)-family is believed to contribute to the progression of a diverse array of cancers." (PMID 30601871, 2019). "Consistent with this, KRAS proximity to EGFR and its canonical downstream kinases, Raf1 and PI3K P110α decreased with SNARE TKO and increased with SNORD50A/B KO in cancer cells with activating oncogenic KRAS mutations." (PMID 31712554, 2019). "Epidermal growth factor receptors (EGFRs) from human cancer cells are immobilized on the inner walls of HCPCF detected using anti-EGFR antibody conjugated to the SERS-nanotag which enhances the raman intensity of the antigen-antibody interaction." (PMID 30818865, 2019). "Actually, there are many other primary resistance mechanisms, include amplification of the MET gene, EMT, and cancer stem cell-like cells, contributing to the resistance to EGFR TKIs." (PMID 31138318, 2019).